EZH2 (enhancer of zeste 2 polycomb repressive complex 2 subunit)
Diseases named in the same sentence as EZH2 in open-access papers (continued):
Sharing a sentence is not in itself a finding about the gene and the disease.
tumor (continued). "Altogether, these studies highlighted that EZH2 can be considered as an inducer of EMT or cancer aggressiveness in a large range of tumors, but surprisingly, in rare cases, EZH2 was also associated to anti-tumor properties." (PMID 34991274, 2018). "Moreover, the use of such inhibitors will be context-specific according to the role of EZH2 in that specific tumor." (PMID 30510924, 2018). "Notably, our data showed that enforced expression of EZH2 largely abrogated the anti-tumor effect of the combination of elemene and gefitinib, indicating that EZH2-dependent mechanism is critically involved in the action of combinative treatment." (PMID 30555330, 2018). "The overall findings indicate that EZH2 regulates tumor cell growth by repressing RBPMS." (PMID 30555699, 2018). "In the context of tumor cells, it was shown to work as a chromatin modifier through the recruitment of EZH2 to the promoter of target genes, as a competing endogenous RNA, sponging let-7, and also as the precursor for miR-675, in turn involved in tumorigenesis." (PMID 29643989, 2018). "Another approach to treat this tumor is based on 3-deazaneplanocin-A (DZNep) blocking EZH2." (PMID 30510924, 2018). "Furthermore, protein recovery was significantly lower in the intermediate grade (GS ≤ 7) compared with normal tissues, and the same trend was observed for the aggressive tumor group (GS > 7), suggesting a loss of gene expression control by JMJD3 and EZH2." (PMID 29805743, 2018). "This implied that combinative therapy might also impact host anti-tumor immune response in a EZH2/PD-L1-dependent manner." (PMID 30555330, 2018). "The mechanism of EZH2 inhibitor tumor suppression was found to be re-expression of p16 and subsequent apoptosis, but this could not be recapitulated in a genetically-engineered mouse model of H3.3-K27M DIPG." (PMID 30340362, 2018). "A prominent example is the ability of EZH2 to function as a tumor suppressor." (PMID 29710783, 2018). "EZH2 is over-expressed in different cancer types, including hematological and solid malignancies, as well as malignant glioma, which is thought to promote tumor progression by silencing tumor suppressor genes." (PMID 29642503, 2018). "Additionally, we summarized and updated the emerging roles of EZH2 in tumor immunity, and EZH2 inhibitors in current pre-clinical and clinical trials in cancer therapy." (PMID 29556394, 2018). "To further support the concept that the anti-metastatic effect of GSK-126 was due to its effect on the tumour cells, we examined the presence of spontaneous metastatic lung lesions in cohorts of wild-type and Ezh2-null Tet-ON PyVmT mice induced with doxycycline for 6 weeks." (PMID 29959321, 2018). "Based on our hypothesis that Ezh2 silences anti-metastatic transcriptional programs in PyVmT tumours, we proceeded to identify potential regulatory factors involved in activating these programs." (PMID 29959321, 2018). "Several of these studies have identified significant pathways and regulators that are modulated in HMCLs upon EZH2 inhibition including contextually relevant oncogenes/tumor suppressors, novel miRNAs, cell-to-cell adhesion/mobility and dysregulation of cell cycle control." (PMID 29774113, 2018). "Furthermore, we summarized and updated the emerging roles of EZH2 in tumor immunity, and current pre-clinical and clinical trials of EZH2 inhibitors in cancer therapy." (PMID 29556394, 2018). "Next, we analyzed the enrichment of H3K27me3 and Ezh2 at the promoters of NGFR, WT1 and MME in these cell lines and human NSCs, and observed that H3K27me3 and Ezh2 were enriched at the promoters of WT1 promoter more than other two gene promoters in all these tumor lines tested." (PMID 29932419, 2018). "The correlation between HIF-1 and EZH2 is an interesting but yet uncharted aspect of tumor biology." (PMID 30510924, 2018). "But EZH2 is essential for tumor-specific T cells-mediated tumor surveillance." (PMID 29556394, 2018).
tumor (continued). "Besides, increased tumor recurrence and progression in patients with NMIBC has been associated with increased E2F and Ezh2 expression in a study that provides a genetically defined model for human high-grade NMIBC." (PMID 30072631, 2018). "Although a variety of signaling molecules contribute to the invasion and metastasis in GBM, we found notably that AXL/EZH2/TGF-β1 might be a key regulator in tumor invasion, migration, and EMT." (PMID 29642503, 2018). "The antagonism between SWI/SNF and PRC2 led some workers to hypothesize that relief of this antagonism in INI1-negative cancers might lead to an over-dependence on PRC2 activity and thereby make these tumours particularly vulnerable to inhibitors of EZH2." (PMID 29685962, 2018). "The link between EZH2 overexpression and tumor progression and aggressiveness might suggest that, conversely, overexpression of histone demethylases might confer tumor suppressive properties to tumor cells or be able to suppress angiogenesis." (PMID 30103412, 2018). "A recent review highlighted the evidence supporting the role of EZH2 in tumor immunity in cancer." (PMID 30555699, 2018). "However, it should be mentioned that several studies show that under some circumstances EZH2 also exhibits tumor suppressive activities." (PMID 30116722, 2018). "Given that Ezh2 has effects on both tumour initiation and metastasis in our model, we next determined whether GSK-126 administration can alter the metastatic potential of established PyVmT tumour cells." (PMID 29959321, 2018). "Interestingly, paired biopsies before and after 4 weeks of treatment in 4 patients with solid tumors revealed target inhibition of EZH2-mediated histone methylation in the tumor tissue in 3 patients." (PMID 30555699, 2018). "We propose that H19 might contribute in more than one way to the EZH2-mediated repression of key anti-tumor genes." (PMID 29643989, 2018). "We reasoned that this set of 83 genes (hereafter “PRC2-inflammatory mediators”) may be enriched for relevant oncogenes driving tumor progression upon Ezh2 inhibition by GSK126." (PMID 30487290, 2018). "Therefore, EZH2 inhibition reactivates the tumor suppressive BAF155/EZH2 target genes to promote apoptosis and inhibit proliferation of CARM1-expressing cells." (PMID 29434212, 2018). "However, functional enrichment analysis using IPA identified EMT as a biological pathway upregulated in Ezh2-null Tet-ON PyVmT tumours, suggesting that a block in EMT is unlikely to explain the impaired metastatic capacity of these tumour cells." (PMID 29959321, 2018). "Interestingly, in this tumor, EZH2 inactivation is accompanied by increased expression of HIF-1α and anti-apoptotic genes, an effect that then causes multidrug resistance." (PMID 30510924, 2018). "Elevated EZH2 expression in UC is strongly associated with aggressive tumour biological behaviour and poor prognosis but does not provide independent prognostic information in this Chinese population." (PMID 30542123, 2018). "Interestingly, aberrant expression of Ezh2 has been widely observed in cancer, with reports of both oncogenic and tumour suppressive functions." (PMID 29959321, 2018). "To test whether Ezh2 inhibition affected tumor cell proliferation in vivo, we performed orthotopic transplantation experiments." (PMID 30487290, 2018). "Additionally, EZH2 also promotes tumor angiogenesis and EZH2 inhibition has been shown to inhibit the differentiation of cancer stem cells into endothelial cells." (PMID 30103412, 2018). "Both EZH2 and its associated PRC2 complex proteins have efficacious small molecule inhibitors that work independently as well as synergistically to reduce cancer cell proliferation and tumor growth in various types of cancers." (PMID 29710783, 2018). "The EZH2 antibody, in contrast, stained the nucleus of tumor cells." (PMID 29673125, 2018). "HMGA proteins show actions consistent with those of EZH2 in promoting tumours and proliferation." (PMID 29853899, 2018).
tumor (continued). "We showed that the catalytic activity of EZH2 is required for acceleration of tumor progression." (PMID 29178021, 2018). "Indeed, both these enzymes have been involved in EMT and tumor aggressiveness in various cancer cell types, and this review will specifically focus on the roles of EZH2 and KDM6B on the epigenetic regulation of EMT." (PMID 34991274, 2018). "Furthermore, tumour progression in humans with NMIBC is associated with increased E2F and EZH2 expression and EZH2 mediated gene expression inhibition." (PMID 30542123, 2018). "While most of the reports had suggested that EZH2 might act as an oncogene, a few studies have demonstrated the tumor suppressor role of EZH2 in the context of MM." (PMID 30555699, 2018). "Moreover, they all found that an inverse relationship between lncRNA XIST and miR-101, and knockdown of lncRNA XIST exerted its tumor-suppressive effects at least in part through regulating miR-101 to modulate EZH2 expression." (PMID 29556138, 2018). "Although higher EZH2 expression harboring smoking-associated sample 1Ad is from higher-grade tumor, the sample 1Ac from never-smoked individual is a metastatic adenocarcinoma." (PMID 29396474, 2018). "Our results suggest, for the first time, that increased EZH2 expression is correlated with tumor progression and may facilitate the accumulation of aberrantly methylated tumor suppressor genes in HNSCC." (PMID 30469511, 2018). "In fact, as recently demonstrated, our knowledge of the role of EZH2 as a tumor suppressor or tumor promoter is still too limited, and new players and interlinked pathways must be detailed and studied before we can provide a valid antitumor strategy that uses inhibitors of EZH2." (PMID 30510924, 2018). "Inhibition of Ezh2 function could also be an interesting alternative for therapeutic intervention during tumor progression as shown by promising early results with the Ezh2 inhibitor 3-deazaneplanocin (DZNep)." (PMID 30072631, 2018). "Therefore, it is of particular interest to investigate for the regulation of EZH2 expression in Tregs in tumor microenvironment." (PMID 29556394, 2018). "Interestingly, SPRY4-IT1 promoted tumor cell proliferation and invasion through activation of EZH2 in HCC." (PMID 29489909, 2018). "Finally, it has been demonstrated that, under hypoxia, HIF-1α regulates the switch from the tumor suppressive to the oncogenic function of EZH2." (PMID 30510924, 2018). "Chronic up-regulation of EZH2 histone methyltransferase is found in a variety of human tumours." (PMID 28587163, 2017). "For instance, combination of EZH2 inhibitors such as deazaneplanocin A (DZNep) or tazemetostat (EPZ6438) with 5-AZA displayed improved therapeutic efficacy of anti-PD-L1 treatment by increasing Teff tumour infiltration and decreasing tumour progression." (PMID 28572863, 2017). "However, after EZH2 knockdown, there was a significant decrease in the drug resistance of tumor cells." (PMID 28968986, 2017). "In contrast, EZH2 functions as a tumor promoter in N-MYC-driven neuroblastoma." (PMID 28505071, 2017). "EZH2 has been reported to control the proliferation of different normal or tumor cell lines." (PMID 27926488, 2017). "Given that EZH2 epigenetically suppresses multiple tumor suppressor miRNAs, we assessed whether EZH2 silenced let-7b and miR-361 in EC cells." (PMID 28088786, 2017). "The EZH2 protein was expressed exclusively in the nuclei of the tumor cells." (PMID 28642877, 2017). "We confirmed (in 145 out of the 148 patients with RNA sequencing data) or evaluated (11 patients with no RNA-sequencing data) the mutation status of EZH2 exons 16 and 18 by genomic PCR in tumor DNA." (PMID 28430172, 2017). "In addition, EZH2 inhibition also led to upregulation of microRNAs reported to be underexpressed in MM as compared with normal plasma cells and with potential tumor suppressor functions." (PMID 28052011, 2017).
tumor (continued). "In addition, Raf-1 kinase inhibitor protein (RKIP), a tumor and metastasis suppressor is repressed by EZH2." (PMID 28410242, 2017). "Furthermore, EZH2 plays a tumorigenic role by epigenetic activation of oncogenic signaling pathways and through promotion of tumor angiogenesis." (PMID 27880940, 2017). "Previously, CXXC4 was identified as a tumor suppressor regulated by EZH2." (PMID 29262584, 2017). "We could show that 2 potential tumor suppressor microRNAs, miR-125a-3p and miR-320c, were reactivated upon EZH2 inhibition." (PMID 28664185, 2017). "Regardless of the specific mechanism, the commonality in all these cases is that cells become dependent on EZH2 to preserve their self-renewal potential, as a consequence of the cellular changes induced by transformation and other alterations occurring during tumor growth." (PMID 28718414, 2017). "Therefore, it was concluded that immunohistochemical analysis of CSC markers, such as ALDH1 and EZH2, can be applied as a predictor of tumor aggressiveness in PCa." (PMID 28415635, 2017). "Indeed, it was shown that prolonged inhibition of EZH2 results in GB tumor progression whereas short-term inhibition improves survival in animal models." (PMID 29234674, 2017). "Because EZH2 has been considered to be a tumour-promoting gene, we hypothesized that its function could be context-dependent in human metastases." (PMID 28429794, 2017). "We demonstrate here that over-expression of aberrant MUC1 glycoform amplifies the inflammatory signal induced by AOM/DSS treatment and establishes a positive regulation of inflammatory cytokines, mediated by p65 and EzH2, which positively controls tumor growth and progression." (PMID 29285251, 2017). "In this review article, we summarized and updated the researches related to miRNAs and lncRNAs in regulation of EZH2, oncogenic and tumor suppressive roles of EZH2 in cancer progression, as well as current pre-clinical and clinical trials of EZH2 inhibitors in cancer therapy." (PMID 28561778, 2017). "Loss of SWI/SNF subunits leads to deregulation of tumor-associated pathways such as Wnt/β-catenin or Hedgehog/GLI and deregulation of epigenetic modulators such as histone deacetylases (HDAC) and Enhancer of Zeste Homolog 2 (EZH2)." (PMID 28714904, 2017). "Kaplan Meyer analysis of these two groups revealed that a statistically significant early tumor recurrence was associated with patients showing high EZH2 and negative Ser21-P EZH2 expression." (PMID 28060766, 2017). "Enhanced tumor immunity by Ezh2S21A-Pmel-1 cells could potentially result from increased expression of overall Ezh2 protein." (PMID 29242551, 2017). "In addition, EZH2 has the ability to interfere with apoptotic pathways and immune evasion by repressing tumor suppressors, immune, cytokine and chemokine receptors." (PMID 28265786, 2017). "Knockdown of EZH2 protein by RNA interference results in growth inhibition in several tumor models." (PMID 28261562, 2017). "Although some studies have shown that EZH2 could inhibit cancer progression, the oncogenic roles of EZH2 in tumor progression, malignancy, and poor prognosis still constitute to be mainly accumulated." (PMID 28561778, 2017). "Indeed, EZH2 has similar effects on tumor cells as KLF2, such as inducing apoptosis and restraining the cell cycle." (PMID 29245984, 2017). "Interestingly, a human cSCC cell subpopulation possesses SC-like features, has enriched expression of Ezh2, Bmi-1, and trimethylated histone H3, and display enhanced ability to drive tumor formation." (PMID 28737694, 2017). "It is known, for example, that the kinase Akt, which is frequently activated in certain tumor types, mediates phosphorylation of EZH2 at Ser21, leading to its reduced affinity for histone H3, reduced H3-K27me3 and consequent derepression of EZH2-silenced genes." (PMID 28758948, 2017).
tumor (continued). "EZH2 is core component of the polycomb repressive complex 2, which catalyzes trimethylation of lysine 27 in histone 3 (H3K27me3), inducing chromatin compaction and preventing the transcription of target genes which are mostly tumor suppressor genes." (PMID 29202777, 2017). "Furthermore, previous studies have shown that lncRNA can influence tumor biology via binding to EZH2 in various cancers." (PMID 28423699, 2017). "We confirmed that both H3K27me3 and EZH2 were decreased in these Ezh2flox/flox tumours by IHC." (PMID 28387316, 2017). "Altogether, knockdown of XIST suppresses tumor growth via regulation of miR-101/EZH2 axis in vivo." (PMID 29100288, 2017). "For example, MALAT1 or UCA1 could play important roles in facilitating genome-wide occupancy of EZH2 onto chromatin in tumor cells." (PMID 29050269, 2017). "In addition, EPZ-005687 and EPZ-011989 decrease histone H3K27me3 mark and kills lymphoma cells with heterozygous mutant EZH2 (Tyr 641 and Ala 677) and inhibits tumor growth of human B cell lymphoma cells." (PMID 28561778, 2017). "Indeed, both types of mutations have been reported in other hematologic malignancies leading to biologic and clinical outcomes that indicate context-dependent tumor suppressor or oncogenic function of EZH2." (PMID 28623912, 2017). "MiR-524-5p and miR-324-5p exhibit a strong tumor-suppressive effect by targeting EZH2." (PMID 29221202, 2017). "This study presents a novel mechanism of EZH2 action in MM pathogenesis by regulating the expression of miRNA genes with tumor suppressor functions and further supports the notion of EZH2 as potential therapeutic target in MM also indirectly affecting the expression of MM-associated oncogenes." (PMID 28052011, 2017). "In addition, it is reported that EZH2 acts a critical factor in promoting tumor growth and metastasis in many malignant tumor models." (PMID 28415635, 2017). "Third, although the established function of EZH2 in tumorigenesis is known to require H3K27 trimethylation with transcriptional silencing of tumor-associated genes, several recent studies have shown some non-established functions of EZH2." (PMID 28418882, 2017). "Similarly, phenotypic reversions of cancer phenotypes have been accomplished by the targeted knockdown of EZH2, with subsequent effects on H3K27me3 levels and target gene expression, in studies on a variety of tumour cells." (PMID 28587163, 2017). "EZH2 silences multiple miRs identified as tumour suppressors." (PMID 29079534, 2017). "The enhancer of zeste homolog 2 (EZH2) is important in tumor development and progression EZH2 may also be a substrate for GSK-3." (PMID 27999207, 2017). "Specifically, Ezh2 is required for survival of these cells and tumor formation." (PMID 28737694, 2017). "Our results suggest that reactivating tumor suppressor miRNAs by targeting EZH2 may be a promising approach for EC treatment." (PMID 28088786, 2017). "In addition to the function of miRNAs as tumor suppressors against EZH2; however, some miRNAs co-expressed with EZH2 activates oncogenic pathways." (PMID 28561778, 2017). "Indeed, it has been shown that EZH2 inhibits the expression of several tumor suppressor genes such as P16 INK4a, E-cadherin, BRCA1 and the adrenergic receptor β2." (PMID 28933369, 2017). "On the basis of this knowledge and our observations, transcriptional upregulation of EZH2 and down regulation of its regulator let-7 in atypical samples suggest that increased methylation in atypical tumours might be related to deregulated PRC2 activity." (PMID 28195122, 2017). "In the present study, we hypothesized that EZH2 inhibition induced apoptosis in bulk tumor cells and CSCs in MM." (PMID 27926488, 2017).